PRKCH (protein kinase C eta)
Description:
Calcium-independent, phospholipid- and diacylglycerol (DAG)- dependent serine/threonine-protein kinase that is involved in the regulation of cell differentiation in keratinocytes and pre-B cell receptor, mediates regulation of epithelial tight junction integrity and foam cell formation, and is required for glioblastoma proliferation and apoptosis prevention in MCF-7 cells. In keratinocytes, binds and activates the tyrosine kinase FYN, which in turn blocks epidermal growth factor receptor (EGFR) signaling and leads to keratinocyte growth arrest and differentiation. Associates with the cyclin CCNE1-CDK2-CDKN1B complex and inhibits CDK2 kinase activity, leading to RB1 dephosphorylation and thereby G1 arrest in keratinocytes. In association with RALA activates actin depolymerization, which is necessary for keratinocyte differentiation. In the pre-B cell receptor signaling, functions downstream of BLNK by up-regulating IRF4, which in turn activates L chain gene rearrangement. Regulates epithelial tight junctions (TJs) by phosphorylating occludin (OCLN) on threonine residues, which is necessary for the assembly and maintenance of TJs. In association with PLD2 and via TLR4 signaling, is involved in lipopolysaccharide (LPS)-induced RGS2 down-regulation and foam cell formation. Upon PMA stimulation, mediates glioblastoma cell proliferation by activating the mTOR pathway, the PI3K/AKT pathway and the ERK1-dependent phosphorylation of ELK1. Involved in the protection of glioblastoma cells from irradiation-induced apoptosis by preventing caspase-9 activation. In camptothecin-treated MCF-7 cells, regulates NF-kappa-B upstream signaling by activating IKBKB, and confers protection against DNA damage-induced apoptosis. Promotes oncogenic functions of ATF2 in the nucleus while blocking its apoptotic function at mitochondria. Phosphorylates ATF2 which promotes its nuclear retention and transcriptional activity and negatively regulates its mitochondrial localization. Product of an upstream open reading frame (ORF) of PRKCH which regulates translation of the downstream protein kinase C eta (PKC-eta) ORF. Functions as a repressive element that maintains low basal levels of PKC-eta in growing cells but enhances its expression during stress conditions induced by amino acid starvation in a EIF2AK4/GCN2-dependent manner. In addition to its role in regulating PKC-eta translation, also inhibits the kinase activity of PKC-eta as well as other protein kinases including PRKCD, PRKCQ and PRKCE but not PRKCA, PRKCG or PRKCZ.
Synonyms: PKCL; PRKCL; uORF2; PKC-L; nPKC-eta
Tractability: Small molecule: an approved drug acts on it; a structure with a bound ligand is known; a high-quality ligand is known; it belongs to a druggable protein family. Antibody: its Gene Ontology location is reachable by antibodies, with high confidence; the Human Protein Atlas places it where antibodies can reach. PROTAC: ubiquitination databases record sites on it; its protein half-life has been measured; a small molecule that binds it is known.
Target class: Kinase; AGC protein kinase PKC family; Protein Kinase; AGC protein kinase group; Enzyme; AGC protein kinase PKC eta subfamily
Gene: Protein-coding gene on chromosome 14 (61,187,559 to 61,550,980, forward strand). Ensembl gene ENSG00000027075.
Subcellular location: Cytoplasm
Subcellular location (Human Protein Atlas): Cytosol; Plasma membrane
Pathways (Reactome):
Hemostasis: Effects of PIP2 hydrolysis
Signal Transduction: G alpha (z) signalling events
Gene Ontology:
Molecular function: enzyme binding; protein binding; protein kinase activity; protein serine kinase activity; diacylglycerol-dependent serine/threonine kinase activity; protein serine/threonine kinase activity; ATP binding; diacylglycerol-dependent, calcium-independent serine/threonine kinase activity; small GTPase binding
Biological process: negative regulation of glial cell apoptotic process; positive regulation of B cell receptor signaling pathway; positive regulation of glial cell proliferation; protein phosphorylation; regulation of bicellular tight junction assembly; intracellular signal transduction; positive regulation of keratinocyte differentiation; positive regulation of macrophage derived foam cell differentiation; positive regulation of protein localization to plasma membrane; signal transduction; phospholipase C/protein kinase C signal transduction
Cellular component: cytoplasm; extracellular exosome; plasma membrane; cytosol; cell-cell junction
Genetic constraint (gnomAD): Loss-of-function variants: 25 observed, 74.72 expected, observed/expected ratio (o/e) 0.33, 90% interval 0.24 to 0.47. The upper end of that interval is the gene's LOEUF score, 0.47, which puts it in group 2 of 6, group 1 being the genes least tolerant of losing a copy. Missense variants: 667 observed, 859.95 expected, observed/expected ratio (o/e) 0.78, 90% interval 0.73 to 0.83. Synonymous variants: 295 observed, 322.67 expected, observed/expected ratio (o/e) 0.91, 90% interval 0.83 to 1.01.
Homologues: Orthologues: chimpanzee PRKCH (99% identical), macaque PRKCH (99% identical), dog PRKCH (98% identical), pig PRKCH (98% identical), mouse Prkch (98% identical), rat Prkch (97% identical), tropical clawed frog prkch (77% identical), rabbit PRKCH (74% identical), guinea pig PRKCH (72% identical), zebrafish prkcha (66% identical), zebrafish prkchb (62% identical), Caenorhabditis elegans tpa-1 (41% identical), and 6 more. Paralogues in human: PRKCE (65% identical), PRKCB (35% identical), PRKCA (34% identical), PRKCG (34% identical), PRKCZ (33% identical), PKN2 (33% identical), PRKCI (33% identical), PKN1 (32% identical), PKN3 (30% identical).
Diseases named in the same sentence as PRKCH in open-access papers:
PRKCH is named in the same sentence as 45 diseases in open-access papers, as found by Europe PMC text mining. Sharing a sentence is not in itself a finding about the gene and the disease. The quoted sentences say what the papers report.
breast carcinoma (6 papers, 2014 to 2026). "TMEM30B and PRKCH which are located adjacently on human chromosome 14 have been implicated in brain and breast cancer, respectively." (PMID 24886479, 2014). "Protein kinase C-eta (PKCη), an antiapoptotic kinase of the novel PKC subfamily, is associated with poor prognosis in breast cancer patients." (PMID 41698898, 2026). "PRKCH has been shown to regulate cancer cell proliferation and increase chemotherapy resistance in a variety of cancers, including glioblastoma 64, breast cancer 65, and non-small cell lung cancer." (PMID 38495503, 2024). "The low expression of PRKCH could inhibit the growth of breast cancer cells, which is conversely upregulated expression in breast cancer." (PMID 31215439, 2019). "In addition, PRKCH is involved in drug resistance and regulation of apoptosis in breast cancer and PRKCQ promotes epithelial to mesenchymal transition (EMT) in breast cancer stem cells." (PMID 27144431, 2016). "In addition, PRKCH could contribute to resistance against the breast cancer cell death by inhibiting JNK activity." (PMID 31215439, 2019). "Moreover, we demonstrated that selected genes from this subset (HES1, PRKCH, ELF5 and TM4SF1) did support invasiveness in ER+ breast cancer cells." (PMID 26356672, 2015).
cerebral infarction (5 papers, 2013 to 2021). An ischemic condition of the brain, producing a persistent focal neurological deficit in the area of distribution of the cerebral arteries. "One of these overlaps with PRKCH—encoding a protein kinase associated with cerebral infarction." (PMID 34032215, 2021). "Furthermore, mutations in the PRKCH gene were associated with cerebral infarction." (PMID 33352859, 2020). "A large-scale genetic epidemiological study in Japanese subjects first showed that a nonsynonymous SNP rs2230500 in the PRKCH gene with cerebral infarction." (PMID 24664524, 2014).
Stroke (5 papers, 2012 to 2018). Sudden impairment of blood flow to a part of the brain due to occlusion or rupture of an artery to the brain. "Previous studies showed that the SNP (rs2230500) in PRKCH is associated with the risk of ischemic stroke in the Japanese population and different types of stroke in the Chinese population." (PMID 22808203, 2012). "In a Japanese population, a variant in PRKCH has been associated with small-artery disease, a stroke subtype that is particularly common in this ethnic group." (PMID 23041239, 2012). "Our data provide evidence that the SNP (rs2230500) in PRKCH decreases the risk of CIMT that is a worthwhile predictor of stroke and complement system possibly mediates this process." (PMID 22808203, 2012). "PRKCH variants have been associated with early-onset obesity and increased stroke risk." (PMID 28360945, 2017).
glioblastoma (3 papers, 2013 to 2025). The most malignant astrocytic tumor (WHO grade IV). "Treatment with Phorbol-12-myristate-13-acetate (PMA) which is a known PKC inducer caused significant increases in cell proliferation of human glioblastoma cell lines in a PRKCH-dependent manner." (PMID 40862737, 2025). "MAPK/ERK activation also participated in the protein kinase C-eta isoform-induced proliferation of glioblastoma cells." (PMID 23991044, 2013).
ischemic stroke (3 papers, 2012 to 2017). A stroke disorder caused by obstruction of blood flow to the brain, due to thrombotic (local blood clot formation) or embolic (due to a blood clot or other material traveling from another site) event. "The SNP (rs2230500) in PRKCH (the gene encoding protein kinase C η) is associated with ischemic stroke and cerebral hemorrhage in the Chinese population, but the molecular mechanisms are not clear." (PMID 22808203, 2012).
Obesity (3 papers, 2017 to 2025). Accumulation of substantial excess body fat. "GWAS have identified four of these (INPP5A, ZDHHC2, IQCF6, and PRKCH) to be associated with BMI or obesity." (PMID 40892850, 2025).
heart failure (2 papers, 2016 to 2020). Inability of the heart to pump blood at an adequate rate to meet tissue metabolic requirements. "Furthermore, through literature research, we found that some MYC target genes were previously reported involving the development of heart failure, including STAT3, PRMT1, PRKCH and HSPA4." (PMID 32460775, 2020).
melanoma (2 papers, 2018 to 2025). A malignant, usually aggressive tumor composed of atypical, neoplastic melanocytes. "RT‐PCR analysis of melanoma cell lines A375 and A375 MEK after treatment with IC50 concentrations of KU757 confirmed the downregulation of CD20, CD25 and NDUFA7, as well as the upregulation of PRKCH, BMP2 and ADAMTS9 hub genes (p < 0.05)." (PMID 40135438, 2025).
rheumatoid arthritis (2 papers, 2010 to 2015). A chronic, systemic autoimmune disorder characterized by inflammation in the synovial membranes and articular surfaces. "For rheumatoid arthritis, systemic lupus erythematosus, ankylosing spondylitis and osteoarthritis diseases, those common factors include TNFSF10, CX3CR1, LY96, TLR5, TXN, TIA1, PRKCH, and PRF1." (PMID 26352601, 2015).
acute myeloid leukaemia (1 paper, 2020). "Notably, high PRKCH expression has been associated with poor prognosis in acute myeloid leukaemia." (PMID 33322625, 2020).
atherosclerosis (1 paper, 2012). A disease characterized by the build-up of fatty material and calcium deposition in the arterial wall resulting in partial or complete occlusion of the arterial lumen. "We demonstrated for the first time that the SNP (rs2230500) in PRKCH is associated with CIMT used as a subclinical phenotype for atherosclerosis and complement C3 considered as a signal of the inflammatory process." (PMID 22808203, 2012). "Our results suggest that PRKCH is involved in atherosclerosis, whether the association is mediated through complement system is yet to be determined." (PMID 22808203, 2012). "In the current study, the association between the SNP (rs2230500) in PRKCH and complement C3 was found firstly, and the results showed that the SNP is associated with CIMT that is a subclinical indicator of atherosclerosis." (PMID 22808203, 2012).
blood disease (1 paper, 2021). A disease that occurs in the blood. "The top candidates include TNFAIP3, which has been reported before, but also include other, novel regions, containing genes involved in blood diseases (CYCS), neurological diseases (PRKCH, KCNH5, LRNN1), metabolism (SFRP4, SUMF1), and skin development (ASCL4, RAB27A)." (PMID 34032215, 2021).
breast tumor (1 paper, 2015). "Among estrogen-regulated genes, progestin/PR-A counter-regulated a distinctive subset, including breast tumor progression genes (e.g., HES1, PRKCH, ELF5, TM4SF1), leading to invasiveness." (PMID 26356672, 2015).
epilepsy (1 paper, 2021). A brain disorder characterized by episodes of abnormally increased neuronal discharge resulting in transient episodes of sensory or motor neurological dysfunction, or psychic dysfunction. "Integrating this evidence, we speculate that PRKCH and S1PR5 may induce resistance in patients with drug-treated epilepsy through the CREB pathway." (PMID 34805265, 2021).
gestational diabetes (1 paper, 2022). Carbohydrate intolerance first diagnosed during pregnancy. "Related findings include differential methylation in cord blood in genes ATP5A1, MFAP4, PRKCH, SLC17A4 related to Gestational Diabetes (GDM); and hypermethylation of the LEP gene promoter associated with maternal obesity on the fetal side of the placenta." (PMID 35749371, 2022).
head and neck cancer (1 paper, 2024). A primary or metastatic malignant neoplasm affecting the head and neck. "Studies have shown that PRKCH is linked to improved survival rates in individuals with head and neck cancer, which is consistent with the results of our research." (PMID 38778403, 2024).
Hypertension (1 paper, 2012). The presence of chronic increased pressure in the systemic arterial system. "The SNP (rs2230500) in PRKCH was significantly associated with CIMT (in far wall of left common carotid arteries, P = 0.016; in far wall of right common carotid arteries, P = 0.012) under a recessive model after adjustment for age, gender, smoking, and hypertension." (PMID 22808203, 2012).
hypertrophic obstructive cardiomyopathy (1 paper, 2017). "The 1425G/A SNP in PRKCH increases the risk of hypertrophic obstructive cardiomyopathy in the Chinese population." (PMID 29383124, 2017). "The 1425G/A SNP in PRKCH increased the risk of HOCM (hypertrophic obstructive cardiomyopathy) (OR=1.427, 95% confidence interval, 1.013 to 2.012, P=0.046) under a dominant model." (PMID 29383124, 2017). "The purpose of this study is to investigate the association of the nonsynonymous SNP (1425G/A) in PRKCH gene and hypertrophic cardiomyopathy in a Chinese population." (PMID 29383124, 2017).
opioid use disorder (1 paper, 2024). A substance-related disorder that involves the recurring use of opioids despite negative consequences. "We identified three genes linked to impulsivity—SLCO5A1, PRKCA, and PRKCH—in infants born to mothers with opioid use disorders." (PMID 39238930, 2024).
rheumatic diseases (1 paper, 2015). "We identified a total of eight differentially expressed genes (TNFSF10, CX3CR1, LY96, TLR5, TXN, TIA1, PRKCH, PRF1), each associated with at least 3 of the 4 studied rheumatic diseases." (PMID 26352601, 2015). "By jointly analyzing 6 published microarray gene expression datasets about RA, SLE, OA and AS, we identified eight genes (TNFSF10, CX3CR1, LY96, TLR5, TXN, TIA1, PRKCH, PRF1) presenting general importance to rheumatic diseases." (PMID 26352601, 2015).
cancer (11 papers, 2008 to 2024). A tumor composed of atypical neoplastic, often pleomorphic cells that invade other tissues. "According to the GSEA analysis, PRKCSH was implicated in diverse cancer-linked immune pathways, mainly including adaptive immune response, response to chemokine, cytokine and so on, which reinforced our belief in PRKCH's immune role in tumors." (PMID 38245572, 2024). "The monoallelic loss was most prevalent in PRKCD, PRKCH, PRKCZ, and PRKCQ across different cancer types." (PMID 35174160, 2021). "We found that PRKCB, PRKCH, and PRKCQ levels were directly associated with HLAs scores in almost most cancers, especially for PRKCB, whose elevated expression moderately to strongly controlled the HLA level in 28 cancer types (R ˃ 0.3)." (PMID 35174160, 2021). "The monoallelic loss was most prevalent in PRKCD, then PRKCH, PRKCZ, and PRKCQ across many cancer types compared to other genes." (PMID 35174160, 2021). "The four genes (HES1, PRKCH, ELF5 and TM4SF1) validated above have all been associated with cancer progression." (PMID 26356672, 2015). "It is mostly expressed in epithelial tissues and has been shown to activate the protein kinase cascade that targets CCAAT/enhancer-binding protein alpha (CEBPA), following the same expression as PRKCH in both cancer cell lines." (PMID 25077705, 2014). "Besides, PRKCD, PRKCH, PRKCZ, and PRKCQ were associated with varying degrees of low-level CNGs along with different cancers." (PMID 35174160, 2021). "By studying the relationship between the activity of PKC genes and the signatures of various immune cell subpopulations, we reported that in most cancer types, the levels of PRKCB, PRKCH, and PRKCQ were positively associated with the infiltration of most immune cells." (PMID 35174160, 2021). "In contrast, PRKCB, PRKCH, and PRKCQ expressions were positively correlated with TLLs among most cancer types." (PMID 35174160, 2021). "The most crucial finding in this study was that PKC isoenzymes are robust biomarkers for the tumor immune status, PRKCB, PRKCH, and PRKCQ as stimulators, while PRKCI and PRKCZ as inhibitors in most cancers." (PMID 35174160, 2021). "Overall the top three enriched targets in the cluster can be classified into immunomodulation, which are PTPN2, protein kinase C beta type (PKC-β), protein kinase C eta type (PKC-η), and protein kinase C gamma type (PKC-γ), cancer, namely, TOPO1, and glucose homeostasis, such as SGLT2." (PMID 26989424, 2016).
tumor (6 papers, 2017 to 2025). "In GBM, another study revealed that an isoform of the protein kinase family, Protein kinase C eta type (PKCη or PRKCH), contributes to tumor progression via activation of ELK1." (PMID 40862737, 2025). "The results showed that METTL7A and PRKCH expression was significantly up-regulated in normal cell lines, while KRT18 expression was significantly up-regulated in tumor cell lines." (PMID 38495503, 2024).
psychiatric disorder (1 paper, 2024). A disorder characterized by behavioral and/or psychological abnormalities, often accompanied by physical symptoms. "We identified dysregulations in four PKC genes—PRKCA, PRKCB, PRKCH, and PRKCI—known for their roles in mood regulation and stress response, crucial for neurodevelopment and linked to psychiatric disorders." (PMID 39238930, 2024).
PRKCH also shares sentences with these, for which no sentence is quoted: glioma (3 papers); and deafness, autosomal dominant 23 (1); ankylosing spondylitis (1); arteriopathy (1); asthma (1); cervical tumors (1); chronic myeloid leukemia (1); gastric atrophy (1); gynecologic cancers (1); head and neck squamous cell carcinoma (1); Hematological Disease (1); Huntington disease (1); infarction (1); infection (1); interstitial lung disease (1); leukemia (1); lung carcinoma (1); microphthalmia (1); neurological diseases (1); non-small cell lung carcinoma (1); ovarian carcinoma (1); systemic lupus erythematosus (1).